RYR2 (ryanodine receptor 2)
Diseases named in the same sentence as RYR2 in open-access papers (continued):
Sharing a sentence is not in itself a finding about the gene and the disease.
ischemia (8 papers, 2014 to 2025). A hypoperfusion of the BLOOD through an organ or tissue caused by a PATHOLOGIC CONSTRICTION or obstruction of its BLOOD VESSELS, or an absence of BLOOD CIRCULATION. "To study the mechanism underlying Ca2+ transients in CMs during ischemia and IR, we next examined the gene expression and protein level of RyR2, which pumps Ca2+ from the endoplasmic reticulum to cytoplasm, and SERCA2a, which tries to dampen the Ca2+ influx." (PMID 40251632, 2025). "Many proteins are degraded during ischemia by the proteolytic action of the 20S proteasome, including ryanodine receptors (RyR2), the calcium release channels located in the sarcoplasmic reticulum (SR)." (PMID 32453773, 2020). "The RyR2 nucleotide binding site is therefore a potential target for cardiac therapeutic agents not only in ischemia but also in other disease states where arrhythmias arise because of irregularities in SR Ca2+-release through RyR2." (PMID 30301919, 2018). "Moreover, whereas both the RyR2 and RyR3 isoforms present in rat brain cortices exhibit endogenous levels of S-glutathionylation and S-nitrosylation, ischemia only increases the S-glutathionylation and S-nitrosylation levels of the RyR2 isoform." (PMID 40076722, 2025). "Accordingly, the cellular sources of ROS that are activated by ischemia and aging may target the RyR2 isoform preferentially." (PMID 40076722, 2025). "However, the expression of RyR2 was significantly decreased following ischemia compared with that in the control group." (PMID 36225189, 2022). "Therefore, we used RyR2 as a representative protein to corroborate the protective effect of ixazomib during ischemia." (PMID 27529620, 2016). "RyR2 protein content decreased by 50% after ischemia and remained at this level after reperfusion; the presence of ixazomib during ischemia prevented the decrease in RyR2 at 0.1 but not at 1 μmol/L." (PMID 27529620, 2016). "To test if the decrease in [3H]-ryanodine binding represents a true decrease in RyR2 protein content and does not result from RyR2 modifications that occurred during ischemia and affected the opening of the channel, we also quantified RyR2 content in western blots." (PMID 27529620, 2016).
type 2 diabetes (8 papers, 2013 to 2025). "Since it was difficult to control for the severity of type 2 diabetes in human donors, RyR2 immunolabeling studies were repeated in a mouse model of obesity-associated type 2 diabetes induced by high fat diet (HFD)." (PMID 23516528, 2013). "Fewer studies have investigated changes in RyR2-mediated Ca2+ handling in models of Type 2 diabetes." (PMID 30425651, 2018). "Together, these studies implicate that the chronic gain-of-function defect in RyR2 due to CaMKII hyperphosphorylation is a novel mechanism that contributes to pathogenesis of type 2 diabetes." (PMID 23516528, 2013). "Moreover, it has been shown that cardiomyocytes contraction and Ca2+ signaling were depressed in the type 2 diabetic rat model together with reduced RyR2 expression level." (PMID 38464201, 2024). "Our study in the S2814D mouse model elucidates the gain-of-function defect in RyR2 due to CaMKII hyperphosphorylation as a novel mechanism that alters insulin secretion due to β cell dysfunction, thereby contributing to the development of type 2 diabetes." (PMID 23516528, 2013). "Our findings suggest that this novel mechanism of CaMKII-mediated phosphorylation of RyR2 in pancreatic β cells contributes to the development of type 2 diabetes and may aid in the development of future therapeutic targets to regulate insulin secretion under pathological conditions." (PMID 23516528, 2013). "It has been demonstrated that blockade of CaMKII and inhibition of RyR2 phosphorylation in cardiac disease improves intracellular Ca2+ homeostasis and attenuates arrhythmogenesis, including in a rat model of type 2 diabetes, but this is also not a universal finding." (PMID 30425651, 2018).
asthma (7 papers, 2013 to 2025). "To detect additional variants in the top-ranked RYR2 asthma gene across populations, we imputed untyped SNPs in RYR2 using haplotypes from the 1000 Genomes Project as reference panels." (PMID 23829686, 2013). "Using genotypes inferred through imput-ation, we uncovered additional RYR2 variants (rs2685301 in African-Americans and rs2779359 in Hispanic-Americans) that exhibited moderate association with asthma and significant LD with genotyped SNPs." (PMID 23829686, 2013). "Imputation analyses based on the 1000 Genomes Project uncovered additional RYR2 variants associated with asthma." (PMID 23829686, 2013). "Recent research demonstrated the association between RYR2 and asthma by genome-wide analysis." (PMID 31480292, 2019). "RyR2 deficiency rendered the CD4+ T cell pool immune suppressive and caused it to behave in the same manner as Foxp3+ Tregs in viral infection, asthma, hypersensitivity, colitis, and tumor development." (PMID 38099494, 2023). "Additional studies are necessary to further elucidate biological roles of RYR2 and pathways related to RYR2 genes in asthma pathogenesis." (PMID 23829686, 2013). "Our rank-based genome-wide analysis revealed for the first time an association of RYR2 variants with asthma and replicated previously discovered PDE4D asthma gene across human populations." (PMID 23829686, 2013). "In an OVA sensitization–induced asthma model, infusion of Tregs or Ryr2–/– Tconvs was equally effective in limiting bronchoalveolar lavage fluid cell number counts, with reductions to a similar degree in both lymphocytes and eosinophils (sensitization schedule and histology)." (PMID 38099494, 2023). "Among the genes mapped from the top 100 loci of African-Americans, Ryanodine receptor-2 (RYR2 [MIM 180902]) has been implicated in the calcium response that leads to increased airway contraction and extensive airway narrowing, which characterizes a key event underlying asthma." (PMID 23829686, 2013). "Knockdown of RYR2 also inhibited the increase in proinflammatory cytokines, including IL-1β, IL-6, and TNF-α, in rats with asthma and spinal cord injury." (PMID 37422673, 2023). "For instance, in the asthma study by Yang and Wang detailed above, the knockdown of MALAT1 reversed inflammation and mitigated bronchial and tracheal smooth muscle cell injury through the regulation of miR-133a and RyR2." (PMID 37250901, 2023).
diabetic cardiomyopathy (7 papers, 2011 to 2024). Diabetic cardiomyopathy is a disorder of the heart muscle in people with diabetes. "In the Diabetic cardiomyopathy pathway, CaMKII is involved in myocardial contraction by interacting with RyR2 protein and causing contractile dysfunction." (PMID 35767566, 2022). "Downregulation of key Ca2+-handling proteins like sarco(endo)plasmic reticulum Ca2+-ATPase (SERCA)2a and ryanodine receptor (RyR2) is one of the major cause of abnormal Ca2+ homeostasis in diabetic cardiomyopathy." (PMID 22054019, 2011). "Our study provides strong evidence in support of the increased ROS, RCS, and RyR2 phosphorylation levels in myocardium contributes to the pathogenesis of diabetic cardiomyopathy." (PMID 38961333, 2024). "Numerous studies have demonstrated that Rb1 ameliorates diabetic cardiomyopathy and myocardial ischemia by inhibiting RyR2 activity to regulate calcium signaling." (PMID 38961333, 2024). "Inhibition of oxidative and carbonyl stress and phosphorylation of RyR2 have been suggested to deeply evaluate the therapeutical targets in diabetic cardiomyopathy." (PMID 38961333, 2024). "Oxidative stress may contribute to cardiac ryanodine receptor (RyR2) dysfunction in diabetic cardiomyopathy." (PMID 38961333, 2024). "Another major finding of the present study is that phosphorylation RyR2 at S2808 by carbonylation oxidative stress is important mechanisms of diabetic cardiomyopathy; Rb1 and insulin treatment is more efficacious way to reduce the process of phosphorylation RyR2." (PMID 38961333, 2024). "Here, we report that reduced RYR2 protein levels alter calcium handling to show a trend to increased calcium amplitude and reduced relaxation kinetics, matching other transgenic models of reduced Ryr2 expression and diabetic cardiomyopathy." (PMID 39041002, 2024). "Moreover, the present study establishes that the mechanism of Rb1 in diabetic cardiomyopathy involves ROS, RCS, and RyR2." (PMID 38961333, 2024).
myocardial ischemia (7 papers, 2012 to 2026). A disorder of cardiac function caused by insufficient blood flow to the muscle tissue of the heart. "We also found that the expression of p-RyR2 in myocardial tissue increased after myocardial ischemia in rats, and this increased expression was mitigated by CHSSC." (PMID 36225189, 2022). "TNF-α-induced caspase-8 activation results in the leakage of RyR2 channels that promote cardiac remodeling after myocardial ischemia/reperfusion." (PMID 33796569, 2021). "RyR2, the calcium release channel of the sarcoplasmic reticulum is reduced by half after myocardial ischemia in adult hearts or after simulated IR in neonatal cardiomyocytes." (PMID 27529620, 2016). "Although 1134 potential targets of miR-376b-5p were predicted, only a few of them have been reported to be involved in myocardial ischemia, including insulin-like growth factor 2 mRNA binding protein 2, ryanodine receptor 2 and BDNF." (PMID 22396777, 2012). "Studies have shown that activation of CaMKII can be detected in the initial stage of cardiac ischemia/reperfusion, and activation of CaMKII can result in RyR2 channel opening through phosphorylation of Ser2814 on RyR2, thereby increasing SR Ca2+ release, which regulates myocardial contraction." (PMID 36225189, 2022). "However, our study showed that after myocardial ischemia, both RyR2 (Ser2814) and RyR2 (Ser2808) were phosphorylated, and the FKBP12.6-RyR2 complex dissociated even when activation of PKA was inhibited." (PMID 36225189, 2022). "Furthermore, activation of the Ser2808 phosphorylation site on RyR2 after myocardial ischemia was significantly inhibited following treatment with CHSSC, while phosphorylation at Ser2814 was not significantly inhibited, and dissociation of the FKBP12.6-RyR2 complex was inhibited." (PMID 36225189, 2022). "Myocardial ischemia, or other disease factors, result in dissociation of the FKBP12.6 and RyR2 complex." (PMID 36225189, 2022). "We also showed that under the condition of myocardial ischemia, CaMKII is not only involved in regulating the phosphorylation of Ser2808 site on RyR2 but Ser2814 site may be, in addition, Ser2808 site probably the main site of CaMKII acting on RyR2 under this condition." (PMID 36225189, 2022). "After myocardial ischemia, the intracellular Ca2+ content was increased, and CHSSC treatment mitigated this increase, down-regulated the levels of p-CaMKII, CaMKII, p-RyR2, and RyR2, and up-regulated the levels of p-RyR2 (Ser2808) and p-RyR2 (Ser2814)." (PMID 36225189, 2022).
Bradycardia (6 papers, 2014 to 2025). A slower than normal heart rate (in adults, slower than 60 beats per minute). "Although bradycardia has been previously reported in patients with RYR2 variants, its presence in individuals with CPVT due to TRDN variants, as shown in this report, is not well documented." (PMID 40760564, 2025). "An in-frame deletion of exon-3 in the Ryr2 gene in the mouse (Ex3-del+/−) was associated with bradycardia and death." (PMID 32903370, 2020). "In support of this view, we found that upon specifically reducing the expression of the WT RyR2 allele, heterozygous Ex3-del mutant mice exhibited bradycardia and death." (PMID 24743769, 2014). "As RYR2–/–-iPSC-CM also displayed disturbances in the rhythmicity, manifesting bradycardia, we believe that RYR2 is a critical player in the regulation of heart rate." (PMID 32903370, 2020).
idiopathic ventricular fibrillation (6 papers, 2015 to 2024). "The RyR2 mutation associated with idiopathic ventricular fibrillation confirmed as a loss-of-function mutation exhibiting Ca2+ release deficiency." (PMID 35783865, 2022). "To this end, we have functionally screened 18 RyR2 mutations that are associated with idiopathic ventricular fibrillation (IVF) or sudden death." (PMID 33825858, 2021).
lung adenocarcinoma (6 papers, 2019 to 2025). A carcinoma that arises from the lung and is characterized by the presence of malignant glandular epithelial cells. "Ryanodine receptor type 2 (RYR2) is a large calcium channel that has been identified as one of the most frequently mutated genes in lung adenocarcinoma (LUAD)." (PMID 40200715, 2025). "The mutation of RYR2 is a significant biomarker associated with high TMB in lung adenocarcinoma." (PMID 31480292, 2019). "Considering the association between RYR2 mutational status and smoking history, mutations in RYR2 might be accumulated during the history of tobacco exposure and play roles as passenger mutations to impact the process of lung adenocarcinoma." (PMID 31480292, 2019). "Here, we found that the PS score of the RYR2 gene is dominantly enriched in two main subtypes of non-small cell lung cancer, lung adenocarcinoma (LUAD) and lung squamous cell carcinoma (LUSC)." (PMID 41154723, 2025).
head and neck cancer (5 papers, 2021 to 2024). A primary or metastatic malignant neoplasm affecting the head and neck. "By using data from the TCGA database, we evaluated RYR2’s predictive performance in head and neck cancer, especially oral cancer." (PMID 39408657, 2024).
Hypertension (5 papers, 2015 to 2024). The presence of chronic increased pressure in the systemic arterial system. "The four individuals with the RyR2 missense variant presented with a high BMI (28-33 kg/m2) and hypertension from an early age." (PMID 38444585, 2024). "Work from Jon Lederer’s lab around the turn of the millennium revealed reduced functional coupling between CaV1.2 channels and RyR2 during HF secondary to hypertension or MI." (PMID 35069264, 2021). "Together, S107, like RyR2 KO, restores the aberrant CH-evoked SR Ca2+ leak in PASMCs and blocks PA vasoconstriction, remolding, and hypertension." (PMID 32669538, 2020). "We focus here on changes observed in CaV1.2 and RyR2 calcium channels during HF with reduced ejection fraction (HFrEF) which commonly occurs after cardiac injury eg. ischemia, or with sustained stress eg. hypertension." (PMID 35069264, 2021).
metabolic syndrome (5 papers, 2015 to 2024). A cluster of metabolic risk factors for CARDIOVASCULAR DISEASES and TYPE 2 DIABETES MELLITUS. "In the prediabetic animal model of metabolic syndrome, the integrity of RyR2 was assessed by Ser 2809 phosphorylation, in addition to the receptor's ability to bind [3H]ryanodine." (PMID 33274235, 2020). "In a more recent study on rats with metabolic syndrome, induced by a 16-week high-sucrose diet, cardiomyocytes exhibited altered Ca2+ signaling that was partly attributed to increased phosphorylation and altered RyR2 function." (PMID 33274235, 2020).
schizophrenia (5 papers, 2020 to 2023). A major psychotic disorder characterized by abnormalities in the perception or expression of reality. "However, there are few known links between genetic risk for TOF and for schizophrenia (apart from e.g., 22q11.2 deletions, 1q21.1 duplications, and deleterious variants in RYR2)." (PMID 33526774, 2021). "Moreover, RYR2 variants have also been sporadically reported in individuals with early onset schizophrenia or ID, and its constraint values suggest intolerance to loss-of-function." (PMID 32536973, 2020). "Among highly ranked genes lacking SFARI Gene scores and OMIM annotations, previous studies suggest association with NDDs and schizophrenia [OBSCN, PLEC, RYR2, ZSWIM8], cortical formation and thickness [LAMA5, GOLGA3), and neurodegenerative diseases (PKHD1, DNAH1]." (PMID 35596027, 2023).
cervical cancer (4 papers, 2020 to 2022). A primary or metastatic malignant neoplasm involving the cervix. "RYR2 somatic mutation is widely observed in cervical cancer patients, and it is speculated that RYR2 can be used as a target for cervical cancer treatment." (PMID 34888385, 2021). "The role of RYR2 in cervical cancer has not yet been described but has previously been identified as a frequently altered gene in cervical cancer samples collected for the TCGA database." (PMID 36201462, 2022).
colorectal cancer (4 papers, 2018 to 2024). A primary or metastatic malignant neoplasm that affects the colon or rectum. "Alterations in RYR2 expression levels have been implicated in the development and progression of a number of tumor types, including non-small cell lung cancer, colorectal cancer, esophageal cancer, and breast cancer." (PMID 39408657, 2024). "PEG3 and RYR2 displayed a significant higher association with early colorectal cancer (onset age ≤ 45)." (PMID 29937994, 2018). "We speculate that the heterogeneity that exists between tumors causes RYR2 to exhibit different functions in colorectal cancer or due to the insufficient sample size of the analyzed data." (PMID 35975176, 2022). "In particular, high expression of RyR2 in colorectal cancer patients has been found to result in shorter survival times." (PMID 39408657, 2024). "Through bioinformatics analysis combined with molecular strategies, RyR2 was identified as a regulator of colorectal cancer metastasis." (PMID 36453019, 2023).
Duchenne muscular dystrophy (4 papers, 2018 to 2023). Duchenne muscular dystrophy (DMD) is a neuromuscular disease characterized by rapidly progressive muscle weakness and wasting due to degeneration of skeletal, smooth and cardiac muscle. "A total of 15,318 circRNAs have been identified in the human heart, and highly expressed circRNA correspond to key cardiac genes, including titin, ryanodine receptor 2, and Duchenne muscular dystrophy." (PMID 31991759, 2020).
esophageal adenocarcinoma (4 papers, 2021 to 2023). A malignant tumor with glandular differentiation arising predominantly from Barrett mucosa in the lower third of the esophagus. "In addition, the RYR2 mutation correlated with better prognosis was involved in the immune response and enhanced antitumor immunity in esophageal adenocarcinoma." (PMID 35874676, 2022).
Intellectual disability (4 papers, 2018 to 2024). "In addition, RyR2 mutations have been implicated in intellectual disability and genetic generalized epilepsy, which is not surprising given that RyR2 is expressed in the brain." (PMID 39777228, 2024). "RYR2 de novo mutations have been identified in patients with intellectual disability and activation of ITPR1 and RYR2 can lead to the release of Ca2+ from intracellular stores affecting propagating Ca2+ waves." (PMID 30148849, 2018).